SNORD115-5 (small nucleolar RNA, C/D box 115-5)
Synonyms: HBII-52-5
Gene: Small nucleolar RNA gene on chromosome 15 (25,178,738 to 25,178,819, forward strand). Ensembl gene ENSG00000200503.
Gene Ontology:
Biological process: RNA processing
Cellular component: nucleolus
Homologues: Orthologues: chimpanzee SNORD115 (99% identical). Paralogues in human: SNORD115-12 (99% identical), SNORD115-9 (99% identical), SNORD115-10 (98% identical), SNORD115-11 (98% identical), SNORD115-13 (98% identical), SNORD115-20 (98% identical), SNORD115-29 (98% identical), SNORD115-36 (98% identical), SNORD115-40 (98% identical), SNORD115-42 (98% identical), SNORD115-43 (98% identical), SNORD115-14 (96% identical), and 37 more.